GPX4 (glutathione peroxidase 4)
Diseases named in the same sentence as GPX4 in open-access papers (continued):
Sharing a sentence is not in itself a finding about the gene and the disease.
ischemic stroke (continued). "In addition, the SFN used as a Nrf2 activator has been shown to promote GPX4 expression to inhibit the ferroptosis, and finally ameliorate cerebral injury after ischemic stroke." (PMID 40237277, 2025). "Therefore, the positive effects of Lycium barbarum glycopeptide in ischemic stroke are likely mediated through activation of the anti-ferroptotic pathway and the antioxidative System Xc-glutathione-glutathione peroxidase 4 pathway." (PMID 39930986, 2025). "Moreover, it has been observed that GPX4 levels generally decline in brain tissue amid acute ischemic stroke events." (PMID 40376919, 2025). "Our study suggests that DGAT1 inhibition may enhance β-oxidation and mitochondrial function, thereby increasing Gpx4 levels, suppressing ferroptosis, and ultimately exerting neuroprotective effects in ischemic stroke." (PMID 40375180, 2025). "To confirm the crucial role of GPX4 in this process, we constructed GPX4 conditional knockout (CKO) mice to explore whether 15‐PGDH inhibitor SW033291 can still ameliorate ischemic stroke and ferroptosis with GPX4 deficiency." (PMID 38188604, 2024). "Additionally, the amount of MDA and the mRNA expression level of ACSL4 and GPX4 were significantly different between ischemic stroke patients and healthy participants, which was consistent with these results identified in mice." (PMID 36967397, 2023). "In conclusion, our data revealed that AA9 improved brain infarct size and neurological deficits in the mice model of MCAO, and it also inhibits ischemic stroke‐induced neuronal damage, by rescuing iron deposition, ROS accumulation, and GPX4, Nrf2, HO‐1, HMGB1, and NF‐κB p65 expression." (PMID 36852441, 2023). "In addition, selenium supplementation can effectively inhibit GPx4‐dependent iron death and endoplasmic reticulum stress‐induced cell death by promoting GPx4 expression after ischemic stroke." (PMID 36852441, 2023). "Therefore, we investigated whether the regulation of 15‐PGDH on ischemic stroke and ferroptosis was dependent on GPX4." (PMID 38188604, 2024). "Biomarkers validated in animal models—such as serum GPX4 activity and cerebrospinal fluid 4-HNE levels—show marked individual variability among ischemic stroke patients and are strongly influenced by reperfusion timing and comorbidities such as diabetes." (PMID 41425599, 2025). "Current understanding attributes ferroptosis in ischemic stroke to several factors, including intracellular iron accumulation, lipoxygenase activation, GSH depletion, GPX4 inactivation, and system Xc− disruption." (PMID 41425599, 2025). "While the PGE2 degrading enzyme 15‐PGDH degrades PGE2 and subsequently reduces the level of EP4, a receptor of PGE2, which can transcriptionally reduce GPX4 level to promote ferroptosis through CREB and NF‐κB, finally exacerbates ischemic stroke." (PMID 38188604, 2024). "To observe the changes in the four biomarkers CDKN1A, GPX4, PRDX1, and PRDX6 in patients with ischemic stroke, we measured their expression of these four biomarkers in peripheral blood using RT-PCR." (PMID 38360841, 2024). "By reducing GPX4 levels, 15‐PGDH induces enhanced lipid peroxidation in ischemic stroke, leading to a poor prognosis of ischemic stroke." (PMID 38188604, 2024). "Previous results have confirmed that PGE2/EP4 axis and GPX4 mediated the effects of 15‐PGDH on ischemic stroke and ferroptosis, and PGE2/EP4 axis acted upstream of GPX4." (PMID 38188604, 2024). "In this study, these levels of ROS, MDA, GSH, iron and several ferroptosis‐related key proteins, such as GPX4, SLC7A11 and ACSL4, were detected in mice possessing ischemic stroke." (PMID 39233353, 2024). "Under pathological conditions, intracellular GSH depletion and GPX4 inactivation lead to ferroptosis, and GSH and GPX4 are the key regulators of ferroptosis and are closely related to hemorrhagic and ischemic stroke." (PMID 35481263, 2022).
ischemic stroke (continued). "Enhancing the expression of GPX4 and GSH synthesis can inhibit ferroptosis and reduce ischemic stroke injury." (PMID 36425577, 2022). "In a mouse model of ischemic stroke, decreased GSH and Gpx4 activity in neurons have been identified, accompanied with enhanced lipid peroxidation." (PMID 33132849, 2020). "In addition to being a component of GPX4 synthesis, selenium can also augment the transcription of GPX4 via coordinated activation of the transcription factors TFAP2c and SP1 and thus alleviate haemorrhagic or ischaemic stroke." (PMID 39994824, 2025). "In summary, our study indicates that inhibition of 15‐PGDH promotes the activation PGE2/EP4 axis, subsequently transcriptionally upregulates the expression of GPX4 via CREB and NF‐κB, and then protects neurons from ferroptosis and alleviates the ischemic stroke." (PMID 38188604, 2024). "ACSL4 overexpression, GPX4 inhibition and GSH downregulation in ischemic stroke lead to lipoxygenase activation, Ca2+ influx, mitochondrial membrane rupture and inhibition of ferroptosis, effectively attenuating mPTP opening and leading to mitochondrial dysfunction." (PMID 38026442, 2023). "No study has evaluated how Dl-3-n-butylphthalide affects the ferroptosis SLC7A11/GSH/GPX4 signal pathway and blood–brain barrier (BBB) PDGFRβ/PI3K/Akt signal pathways in the rat middle cerebral artery occlusion/reperfusion (MCAO/R) model of ischemic stroke." (PMID 36909944, 2023). "Since oxidative stress is a critical event during ischemic stroke, we assume that CMA might be activated under ischemic stroke, which then participates in ferroptosis by inducing Gpx4 degradation." (PMID 33132849, 2020). "Consistently, glutathione peroxidase 4 (GPX4) and ferritin, two classic markers of ferroptosis, do not change in permanent ischemic stroke rats with or without crocin-treatment." (PMID 36681688, 2023).
bladder cancer (30 papers, 2007 to 2025). "The results revealed a positive association between USP5 and GPX4 RNA levels in bladder cancer tissue." (PMID 40136465, 2025). "7j can cause bladder cancer cells death by regulating the xCT/GPX4/ROS pathway in vitro and exhibits suitable affinity for GPX4." (PMID 34869390, 2021). "We found that RES exerts its anti-bladder cancer effect by activating the ferroptosis pathway linked with oxidation-caused damages such as mitochondrial dysfunction, lipid peroxidation, and downregulation of GPX4 and xCT proteins." (PMID 40535803, 2025). "EVO has also been found to exert its anti-bladder cancer activity by inducing ferroptosis through the inhibition of glutathione peroxidase 4 (GPX4)." (PMID 40729027, 2025). "Our results revealed that the TAZ/NRF2 positive feedback loop inhibited ferroptosis in bladder cancers by regulating GPX4, offering a novel therapeutic potential for patients with BLCA." (PMID 40301305, 2025). "HSPE1 modulates ferroptosis by regulating GPX4/lipid peroxidation in bladder cancer and promotes LUAD malignancy via aerobic glycolysis." (PMID 41375045, 2025). "Key regulators of ferroptosis include the lipid peroxidation pathway, iron metabolism, and glutathione peroxidase 4 (GPX4), which is essential for preventing lipid peroxidation and promoting cell survival in bladder cancer." (PMID 40301305, 2025). "Further studies showed that USP5 interacts with GPX4 and stabilizes GPX4 by inhibiting its ubiquitination These findings revealed USP5 inhibits ferroptosis in bladder cancer cells by stabilizing GPX4." (PMID 40136465, 2025). "FADS2 regulates ferroptosis in bladder cancer by influencing the expression of GPX4 and SLC7A11, but the upstream regulators of FADS2 remain to be explored." (PMID 40682485, 2025). "Collectively, our findings reveal a novel mechanism by which USP5 regulates ferroptosis through GPX4 stabilization, highlighting its critical role in bladder cancer development and progression." (PMID 40136465, 2025). "In conclusion, our study demonstrated that USP5 plays a critical role in bladder cancer progression by promoting cell proliferation and inhibiting ferroptosis through the stabilization of GPX4." (PMID 40136465, 2025). "Glutathione S-transferase zeta 1 (GSTZ1) enhances ferroptosis through the HMGB1/GPX4 pathway in bladder cancer cells, indicating that HMGB1 promotes ferroptosis via inhibiting the pathways related to antioxidant defenses." (PMID 39994144, 2025). "In TGF-β1-induced mesenchymal-like bladder cancer cells, ferroptosis-related genes (GPX4, SLC7A11) were markedly elevated, alongside increased lipid peroxides (LPO) and glutathione (GSH) levels." (PMID 41413023, 2025). "The results revealed a significant positive correlation between USP5 and GPX4 RNA levels in bladder tissue on the basis of the GTEx data and a positive association between USP5 and GPX4 RNA levels in bladder cancer tissue on the basis of the TGCA data." (PMID 40136465, 2025). "For instance, GPX4 degradation and mTOR inhibition mediated by autophagy play a synergistic role in killing bladder cancer cells." (PMID 38526702, 2024). "Taken together, these results demonstrated that GPX4 hold great potential in developing tumor specific controllable nanomaterials against bladder cancer." (PMID 38212623, 2024). "We present a schematic illustration showing EVO-induced ferroptosis through the suppression of GPX4 in human bladder cancer cells." (PMID 37046995, 2023). "Taken together, these results demonstrate that EVO induces ferroptosis in bladder cancer cells, as evidenced by increases in ROS production and lipid peroxidation and the suppression of GPX4." (PMID 37046995, 2023). "The mTOR signaling inhibition upregulates autophagy-mediated GPX4 degradation, thereby promoting ferroptosis of bladder cancer cells." (PMID 36923942, 2023).
bladder cancer (continued). "Unexpectedly, GSH level and GPX4 activity were slightly but significantly elevated in FLRT2‐overexpressed bladder cancer cells, suggesting a compensatory protection of GSH/GPX4." (PMID 37480224, 2023). "Furthermore, a series of rescue experiments further supported the notion that this positive feedback loop influences the proliferation of bladder cancer cells by regulating ferroptosis through the GPX4 pathway." (PMID 40301305, 2025). "Inhibitors of USP5 or its downstream targets, such as GPX4, could be developed as novel therapeutic agents for bladder cancer." (PMID 40136465, 2025). "However, recent research has proposed different perspectives, suggesting that mTOR inhibition can enhance mitophagy-mediated GPX4 degradation, thereby promoting ferroptosis in bladder cancer cells." (PMID 40305351, 2025). "First, we analyzed the correlation between USP5 and GPX4 in bladder cancer." (PMID 40136465, 2025). "Based on the link between GPX4 and other malignancies, GPX4 inhibitors may be extremely useful in slowing the progression of bladder cancer and improving prognosis." (PMID 40969276, 2025). "Additionally, in bladder cancer, although GPX4 acts to inhibit ferroptosis, autophagy facilitates the degradation of GPX4, augmenting the efficacy of Fin56 in stimulating ferroptosis." (PMID 39403142, 2024). "Yet, GSH level and GPX4 activity were unaffected by FLRT2 silence in human bladder cancer cells." (PMID 37480224, 2023). "Additionally, depletion of PSMD14 suppressed bladder cancer cell growth via down-regulation of GPX4, and the promotion of PSMD14-induced cell growth was observably reversed by the GPX4 inhibitor RSL3." (PMID 36632137, 2023). "Depletion of PSMD14 could inhibit the proliferation of bladder cancer cells through the downregulation of GPX4." (PMID 36632137, 2023). "In this study, we observed elevated expression levels of TMBIM6 and ferroptosis-related proteins (GPX4, SLC7A11, and FTH1) in bladder cancer tissues, while CAM expression was significantly downregulated." (PMID 40610429, 2025). "Considering that GPX4 is a key factor in the ferroptosis signaling pathway, we analyzed the correlation between USP5 and GPX4 in bladder cancer via the FerrDb database." (PMID 40136465, 2025). "Building upon these previous findings, our study has made a novel observation in bladder cancer: we identified significantly elevated expression levels of TMBIM6 and ferroptosis-related proteins (GPX4, SLC7A11, and FTH1) in clinical bladder cancer specimens." (PMID 40610429, 2025). "TMBIM6, ferroptosis-related proteins (GPX4, SLC7A11, and FTH1), and calmodulin (CaM) expressions in bladder cancer and paracancerous tissues were obtained by immunohistochemistry." (PMID 40610429, 2025). "TMBIM6 overexpression enhanced proliferation, invasion, migration, GSH/GPX4 levels, and ferroptosis resistance while suppressing MDA, Fe2+, and lipid ROS in bladder cancer cells, effects reversed by Erastin." (PMID 40610429, 2025). "In the context of bladder cancer specifically, baicalin and Fin56 have been shown to induce ferroptosis through distinct molecular mechanisms, targeting FTH1 and GPX4, respectively." (PMID 40610429, 2025). "In an analysis of the expression levels of ferroptosis genes, GPX4, SLC7A11, and GSS were found to be highly expressed in some bladder cancer patients, and ACSL1 and ACSL4 were expressed at low levels." (PMID 36408230, 2022). "Third, the universality of the stability of USP5 to GPX4 in other bladder cancer subtypes still needs further validation, and future studies could explore biomarkers for combined USP5 and GPX4 therapy." (PMID 40136465, 2025). "FIN56 could promote autophagy-mediated GPX4 degradation and induce the ferroptosis of bladder cancer cells, and FIN56 and the mTOR inhibitor Torin 2 synergistically killed bladder cancer cells." (PMID 38247539, 2024).
bladder cancer (continued). "A variety of nano drugs have been reported to specifically adhere to bladder cancer cells and deliver iron through endocytosis when exposed to laser irradiation, resulting in ROS generation and accumulation and subsequent GSH and GPX4 depletion, ultimately leading to ferroptosis." (PMID 36408230, 2022). "There are currently no studies that link GPX4 to bladder cancer growth, invasion, or prognosis." (PMID 40969276, 2025). "In addition, other publicly available data from The Cancer Genome Atlas (TCGA) showed that lower expression of MLL4 was significantly associated with both lower expression of ALOX12 and higher expression of GPX4 in human head and neck SCC as well as bladder cancer." (PMID 34890228, 2021).
cervical cancer (29 papers, 2022 to 2026). A primary or metastatic malignant neoplasm involving the cervix. "GPX4 acts as a key anti-ferroptosis enzyme in cervical cancer, and its downregulation—triggered by MTCH1 deficiency and impaired FoxO1 nuclear translocation—leads to elevated ROS and ferroptotic cell death." (PMID 40895556, 2025). "Moreover, according to the human protein atlas, high GPX4 expression in cervical cancer is associated with a favorable clinical outcome." (PMID 35903697, 2022). "Inhibition of miR-193a-5p or GPX4 overexpression suppressed circACAP2 depletion-induced lipid ROS, iron, and Fe2+ in cervical cancer cells." (PMID 40161373, 2025). "miR-193a-5p targets GPX4, and circACAP2 promotes GPX4 expression by adsorbing miR-193a-5p in cervical cancer cells." (PMID 40161373, 2025). "In cervical cancer, elevated GPX4 expression correlates with chemoradiotherapy resistance, particularly in HPV-positive tumors." (PMID 40895556, 2025). "Another study revealed that circular RNA circACAP2 inhibits ferroptosis in cervical cancer by targeting miR-193a-5p/GPX4 during malignant progression." (PMID 40161373, 2025). "For example, circACAP2 regulates GPX4, a key protein in ferroptosis, through the miR-193a-5p/GPX4 axis, inhibiting ferroptosis and promoting the malignant progression of cervical cancer." (PMID 40630134, 2025). "Many natural products and their active components have been found to induce cervical cancer cell death by modulating the System Xc−-GPX4 axis and lipid, mitochondrial, and iron metabolism in a process known as ferroptosis." (PMID 38738178, 2024). "Meanwhile, CircACAP2 inhibited the expression of miR-193a-5p by sponge-wrapping it, thereby promoting GPX4 expression in cervical cancer cells." (PMID 38392340, 2024). "CircACAP2 directly interacts with miR-193a-5p targeted GPX4 as a competitive RNA (ceRNA) in cervical cancer cells." (PMID 38392340, 2024). "CircRNA ACAP2 inhibits ferroptosis during cervical cancer progression via the miR-193a-5p/GPX4 axis." (PMID 38392340, 2024). "Various ferroptosis-associated traditional signals such as SLC7A11, GPX4, and ACSL4 have been uncovered in cervical cancer, and it seems that circRNAs provide prominence to regulate ferroptosis-related signals in cervical cancer." (PMID 37065473, 2023). "Circular RNA circACAP2 increases GPX4 expression by targeting miR-193a-5p, thereby repressing ferroptosis in cervical cancer during malignant progression by miR-193a-5p/GPX4." (PMID 37025659, 2023). "Altogether, these results confirmed that DHA triggered cervical cancer cells ferroptosis, which was related to GPX4 depletion." (PMID 37065442, 2023). "The study further reported the activity of SLC7A11 and GPX4 in combination with ferroptosis inducers to cervical cancer in vitro and in vivo experiments, and found that tumor cells were considerably more sensitive to radiotherapy." (PMID 37025659, 2023). "Taken together, our study demonstrated evidence that the inhibitory effect of DHA on the proliferation of cervical cancer is related to ferroptosis, mediated by the GPX4 inhibition and ferritinophagy, whereas HO-1 expression is anti-ferroptosis." (PMID 37065442, 2023). "In this work, we explored the role of circACAP2 in cervical cancer and determined that circACAP2 regulated cell ferroptosis through the miR-193a-5p/GPX4 network." (PMID 35847361, 2022). "miR-193a-5p was able to target GPX4, and circACAP2 promoted the GPX4 expression by sponging miR-193a-5p in cervical cancer cells." (PMID 35847361, 2022). "miR-193a-5p was able to target GPX4 and circACAP2 promoted GPX4 expression by sponging miR-193a-5p in cervical cancer cells." (PMID 35847361, 2022). "We then analyzed the expression and correlation of circACAP2, miR-193a-5p, and GPX4 in cervical cancer samples." (PMID 35847361, 2022). "Clinically, the expression of circACAP2 and GPX4 was upregulated, and miR-193a-5p expression was downregulated in clinical cervical cancer samples." (PMID 35847361, 2022).